TLR2 (toll like receptor 2)
Diseases named in the same sentence as TLR2 in open-access papers (continued):
Sharing a sentence is not in itself a finding about the gene and the disease.
periodontitis (continued). "In agreement, population-based studies have shown that during chronic inflammatory diseases such as periodontitis, pulmonary tuberculosis, and cystic fibrosis, hypomethylation of the TLR2 promoter leads to enhanced expression of TLR233,34,46." (PMID 33758175, 2021). "It is known that TLR-4 and TLR-2 expression levels are highly increased in periodontitis lesions, compared to healthy periodontal ligament." (PMID 32714091, 2020). "Our meta-analysis was the first to independently analyze the relationship between TLR-2 and periodontitis, including 18 studies and six common SNPs and some unusual SNPs." (PMID 32831974, 2020). "We consider that the genetic information of TLR2 site has a certain reference value for the diagnosis, prevention, and treatment of chronic periodontitis." (PMID 32831974, 2020). "So far, a number of studies have evaluated the association between PRRs, SNPs, and periodontitis, including CD14, TLR2, TLR4, and MBL2." (PMID 32831974, 2020). "The role of TLR-2 in the pathophysiology of periodontitis has been widely discussed; elevated levels of TLR-2 were found in gingival inflammatory tissue." (PMID 32831974, 2020). "Several periodontopathogens have been identified, of which Pg is one of the bacteria in the initiation and progression of periodontitis and which interacts either via TLR2 or TLR4." (PMID 31817424, 2019). "There are studies demonstrating an increase in TLR2 expression in oral mucosal tissue in patients with chronic periodontitis compared with controls." (PMID 31611734, 2019). "Comparison of healthy and periodontitis tissues showed that periodontitis was characterized by loss of TLR1, TLR2, and TLR5 expression in the superficial epithelial cell layers." (PMID 31448244, 2019). "Elevated TLR2 expression is found in the oral mucosa of patients with chronic periodontitis compared to controls." (PMID 31611734, 2019). "Intracellular expression of TLR-4 and TLR-2 was confirmed by recent report concerning immunohistochemical detection of them in pocket epithelial cells in periodontitis." (PMID 30165815, 2018). "On the other hand, while the sTLR-2 and the paired epithelial cell associated TLR-2 mRNA exhibited a direct correlation (r2 = 0.62), that of sTLR4 and TLR-4 mRNA exhibited an inverse correlation (r2 = 0.53) in the periodontitis cohort." (PMID 30571680, 2018). "Toll-like receptor (TLR)-2 and − 4 are receptors of lipopolysaccharide (LPS) from Porphyromonas gingivalis, a major pathogen of chronic periodontitis." (PMID 29859535, 2018). "In contrast to the findings with P. gingivalis, TLR2−/− mice that were infected with A. actinomycetemcomitans developed periodontitis." (PMID 29163477, 2017). "A negative correlation was found between methylation levels of IL-6 in gingival tissue and probing depth in periodontitis patients, compared to the positive correlation with TLR2 methylation and probing depth." (PMID 29201597, 2017). "TLR2, CatB, and 8-OHdG were expressed in the fibroblasts of inflamed tissues with chronic periodontitis and found to be localized in 89%, 87%, and 86% of fibronectin-positive fibroblasts, respectively." (PMID 27648120, 2016). "Hyperglycemia and chronic periodontitis also lead to upregulation of TLR2 in the gingival tissue of type 2 diabetes patients." (PMID 28536605, 2016). "We recently found that the levels of IL-1β and inflammasome components increased in periodontitis patients and P. gingivalis induced IL-1β release via TLR2/TLR4-NLRP3/AIM2 inflammasome-caspase-1 pathway activation." (PMID 27386246, 2016). "Periodontitis-related bacteremia or invasive dental procedures allow Fusobacterium nucleatum to seed the endothelium, disrupt VE-cadherin, activate TLR2/4 pathways, increase ROS and pro-coagulant mediators, and propagate systemic inflammation via outer membrane vesicles." (PMID 41154402, 2025).
periodontitis (continued). "A hypomethylation of signal transducers and activators of transcription 5 (STAT5) promoter and prostaglandin-endoperoxide synthase 2 (PTGS2) promoter, increased methylation at two CpG sites of TNF-α and TLR2 gene in gingival tissues from chronic periodontitis patients has been reported." (PMID 38130504, 2024). "Our previous research demonstrated that PLAP-1 may inhibit TLR2/4-mediated inflammatory responses, thereby exerting a protective function against periodontitis." (PMID 37958972, 2023). "TLR2-/-, TLR4-/-, TLR2&4-/-, and TLR9-/- mice exhibited the reduced alveolar bone loss in various mouse periodontitis models, suggesting that TLRs indeed played an important role in developing discordant oral barrier immunity." (PMID 38015204, 2023). "Similarly, a positive correlation has been found between TLR-2 promoter hypermethylation in inflammatory cells from gingival tissue biopsies and increased pocket probing depth in periodontitis-affected patients." (PMID 36233348, 2022). "In Tlr2 KO and Tlr4 KO mice, the bone loss caused by ligation-induced periodontitis did not decrease." (PMID 34445604, 2021). "Seven studies with 2857 cases and 2452 controls did not report an association between periodontitis and TLR-2 rs3804100 polymorphism in five gene models (p = 0.269, OR = 0.922, 95% CI: 0.797-1.065)." (PMID 32831974, 2020). "AA: p = 0.035, OR = 0.704, 95% CI: 0.508-0.975).The heterogeneity test for the pooled data sets was not significant (I2 = 0) for the TLR-2 rs1898830 polymorphism in five gene models, indicating the robustness of the meta-analysis for chronic periodontitis." (PMID 32831974, 2020). "Previously, it was reported that RAGE levels were elevated in patients susceptible to periodontitis compared to healthy patients, but TLR2 and TLR4 levels did not change before implant therapy." (PMID 32760399, 2020). "But most of the studies reported TLR-2 gene polymorphism and susceptibility to periodontitis are not consistent." (PMID 32831974, 2020). "In periodontitis an abnormal immune response known as a “hyper-responsive” phenotype was demonstrated by investigations of peripheral blood leukocytes that were stimulated with TLR2 and TLR4 agonists." (PMID 30837987, 2019). "Under chronic inflammatory conditions such as periodontitis in contrast to the TLR2 upregulation expression of TLR4 decreased, which may prevent from inflammatory exacerbation, i.e., tissue and bone destruction through containment of the inflammatory response." (PMID 30837987, 2019). "In order to mimic an enduring bacterial pressure, as is the case during chronic periodontitis, TLR2, TLR4, or a combination of both agonists, were added to the PBMC/PBL cultures and GF cocultures for 21 days, where after the effects on leukocyte survival and selective proliferation were assessed." (PMID 31817424, 2019). "Pertinently, it is interesting that our data demonstrates a negative correlation between the SEC associated TLR-2 mRNA and the sTLR-2 in the gingivitis cohort and not in the periodontitis cohort." (PMID 30571680, 2018). "Moreover, since we used a TLR2 agonist and an unspecific cathepsin inhibitor, this result may have an even broader significance for the understanding of periodontal diseases, because periodontitis is not only caused by a single bacterium or mediated by a single member of the cathepsin family." (PMID 29622023, 2018). "However, de Faria Amormino and co-workers found a higher degree of methylation in TLR2 in samples from periodontitis patients compared to controls." (PMID 29201597, 2017). "Therefore, ablating TLR2 or TLR4 signaling, modifies differentially the susceptibility to develop periodontitis and dependent on mouse strain." (PMID 29163477, 2017). "Interestingly, LPS from the periodontitis pathogen Porphyromonas gingivalis mainly exerts its effect on host cells via TLR2." (PMID 28597116, 2017).
periodontitis (continued). "Our data shows potential interaction between IFN-γ and TLR2 responses in hPDLSCs, which might be involved in regulation of immune response in inflammatory diseases, and particularly periodontitis." (PMID 28993635, 2017). "Soluble salivary TLR2 may be considered a potential prognostic or periodontal health maintenance marker for chronic periodontitis." (PMID 27727278, 2016). "TLR2 activation is critical for human gingival epithelial cells and human macrophages to recognise and respond to T. denticola and both TLR9 and NOD2 have been reported to contribute to P. gingivalis-induced bone loss in an experimental model of periodontitis." (PMID 27035339, 2016). "The pathogenesis of periodontitis is driven by subgingival microbial dysbiosis, where keystone pathogens such as Porphyromonas gingivalis subvert host immunity via lipopolysaccharide (LPS)-mediated activation of the complement 5a receptor 1-Toll-like receptor 2 (C5aR1-TLR2) crosstalk pathway." (PMID 40732209, 2025). "Therefore, the meta-analysis on the relationship between TLR-2 gene polymorphism and periodontitis susceptibility has not been reported alone, while the meta-analysis on TLR-4 and CD14 has been published; the conclusions are still inconsistent." (PMID 32831974, 2020). "Since TLR2 is a central regulator of immune responses to P. gingivalis and is necessary for the development of pathological inflammation in murine models of periodontitis, DNA methylation may be a crucial component of a mechanism controlling GEC responses to this periopathogen." (PMID 33256844, 2020). "Also, receptors such as TLR-4 and TLR-2 are connected to the pathology of periodontitis." (PMID 33093521, 2020). "Since the effect of sCD14 levels on the hPDLSC response to both TLR-2 agonists and bacterial LPS is concentration-dependent, we suggest that alterations of local sCD14 levels might play an important role in periodontitis through sensitizing hPDLSCs to periodontal pathogens." (PMID 31178663, 2019). "Some studies have demonstrated the involvement of TLR2 and TLR4 in the pathogenesis of oral diseases, such as chronic periodontitis and dental caries." (PMID 39000094, 2024). "C57BL/6, C57BL/6 J (WT, -TLR2(KO), -TLR4(KO), -TLR2,&4KO) mice, CD1 Swiss mice, C57BL/6 J female mice are some of the strains, and their knockouts that have been used in experimental periodontitis with microbes." (PMID 39421460, 2024). "Similar findings were reported by De Oliveira and colleagues, observing trends for hypermethylation in TLR2 genes and significant hypomethylation of TLR4 gene profiles in periodontitis tissues compared with healthy samples." (PMID 36291079, 2022). "Possible associations between SNPs in CD14 (rs2569190), NF-κB (rs28362491), TLR2 (rs5743708), and TLR4 (rs4986790) and the occurrence of severe periodontitis were investigated in the cohort of CV patients." (PMID 34305452, 2021). "And indeed, in a variety of case-control studies as well as in meta-analyses, their impact on periodontitis as well as CV diseases was assessed (CD14, NF-κΒ, TLR2, and TLR4)." (PMID 34305452, 2021). "Consistently, distinct TLR2 and TLR4 promoter methylation patterns have been reported in periodontitis and Behçet's disease." (PMID 34031466, 2021). "In both Tlr2 and Tlr4 KO models, the expression of RANKL mRNA in the gingival tissue of ligation-induced experimental periodontitis was still significantly higher than that in the control group." (PMID 34445604, 2021). "Our in vitro study provides original evidence that F. alocis stimulates COX2 production in fibroblastic and monocytic cells through TLR2 and MAPK mechanisms, suggesting a role of this periodontopathogen in the etiopathogenesis of periodontitis." (PMID 32089643, 2020). "Clinical studies have demonstrated that the levels of TLR2 and TLR4 in periodontitis patients were significantly higher than those in control groups." (PMID 32760399, 2020).
periodontitis (continued). "TLR2 and TLR4 are the most extensively researched receptors of the TLR family in relation to periodontitis in mice and men." (PMID 32793243, 2020). "In contrast to these results, others have shown that glycine contributes to inflammation by promoting toll-like receptor 2 to release increased levels of TNF-α, and upregulating bone resorption stimulators prostaglandin E2 and cyclooxygenases in periodontitis." (PMID 33552029, 2020). "TLR2 and TLR4 are essential signaling proteins in progression of inflammation and related bone metabolism in periodontitis." (PMID 32291538, 2020). "Recently, levels of microbial ligands for TLR-2 and TLR-4 have been reported to be higher in the saliva of periodontitis patients." (PMID 30571680, 2018). "While the immunohistochemical or immunofluorescence studies have shown elevated TLR-2 and TLR-4 protein expression in the gingival epithelial cells in periodontitis, molecular analyses of TLR-2 and TLR-4 transcripts have yielded variable results." (PMID 30571680, 2018). "Altered expression profiles of CD14, TLR-2 and TLR-4 have been previously reported in periodontitis." (PMID 30571680, 2018). "We focused on TLR2 and TLR4 activation and noted that IgG from aCL-containing periodontitis sera activate TLR4 in tissue culture." (PMID 30192824, 2018). "Evidence suggests that both TLR2- and TLR4-positive cells are upregulated in the gingival tissues in periodontitis." (PMID 28326084, 2017). "The expression of Toll-like receptor 2 (TLR2), TLR4, TNF-α, and inducible NO synthase was mainly detected in the gingival macrophages of chronic periodontitis patients." (PMID 24363500, 2013). "In the present study, we confirmed that macrophages densely expressed TLR2, TLR4, TNF-α, and iNOS in the gingival tissues of chronic periodontitis patients." (PMID 24363500, 2013). "Moreover, TLR-2 and TLR-4 receptors show significant activity in epithelial cells during stomatitis, as well as periodontitis." (PMID 39684489, 2024). "Collectively, LPS could promote the macrophages into M1 status via TLR2/TLR4/NF-κB p65 signaling pathway partly by sEV-mediated microRNA-433-3p, which could be a potential therapeutic target for periodontitis." (PMID 37351818, 2023). "In a study on HIV-positive North American patients with periodontitis, 8 SNPs in 6 TLR genes (TLR1 (n = 2), TLR2 (n = 1), TLR4 (n = 1), TLR6 (n = 1), TLR8 (n = 2), and TLR9 (n = 1)) were positively associated with P. gingivalis (2 SNPs), T. denticola (6 SNPs), and T. forsythia (1 SNP)." (PMID 35122548, 2022). "Mice lacking either C5Ar or Toll-like receptor-2, on the other hand, are protected from experimental periodontitis." (PMID 35571048, 2022). "SNPs in CD14, NF-κΒ, TLR2, and TLR4 are no risk modulators for preexisting CV events or severe periodontitis in CV patients." (PMID 34305452, 2021). "Based on the data available, we assessed in our study the impact of SNPs in TLR2 (rs5743708), TLR4 (rs4986790), CD14 (rs2569190), and NF-κΒ (rs28362491), on severe periodontitis as well as on the incidence of new CV events within a three year follow-up in a cohort of CV patients." (PMID 34305452, 2021). "High glucose (HG) was shown to induce Toll like receptor 2 (TLR-2), NF-ĸB pathway and IL-1β in human gingival fibroblasts and RAGEs were upregulated on mRNA level in inflamed gingival tissues of T2DM periodontitis patients compared to their non diabetic periodontitis patients." (PMID 34940355, 2021). "Among them, TLR2, TLR4, and TLR9 play important roles in the development of periodontitis." (PMID 34445604, 2021). "TLR2 and TLR4 are the predominant TLRs activated in periodontitis." (PMID 32793243, 2020). "In the same study, a trend toward increased methylation in periodontitis patients has been shown for a specific CpG site, but not for the whole TLR2 promoter." (PMID 33256844, 2020).
periodontitis (continued). "TLR2 and TLR4 are the most widely studied extracellular innate receptors that recognize various PAMPs and are likely to play a role in the pathogenesis of periodontitis." (PMID 33322059, 2020). "Furthermore, the overall aim of the present study was to investigate the effects of chronic exposure to TLR2 and TLR4 agonists on the inflammatory adaptive immune response, mimicking an inflammatory environment such as apparent in chronic periodontitis." (PMID 31817424, 2019). "Therefore, the overall goal of the present study was to investigate the effects of chronic exposure to TLR2 and TLR4 agonists on the inflammatory adaptive immune response, mimicking an inflammatory environment such as apparent in chronic periodontitis." (PMID 31817424, 2019). "PAMPs of TLR2 and TLR4 have been shown to be elevated in saliva of periodontitis patients." (PMID 30571680, 2018). "Although the mechanism through which P. gingivalis-induces bone resorption via TLR2 and TLR4 is not fully understood, our results suggest that TLR-stimulation in periodontitis upregulates alveolar bone resorption under high plasma concentration of oxLDL in dyslipidemia." (PMID 29859535, 2018). "Binding of TLR2 and TLR4 to PAMPs presented on pathogens will induce the expression of ICAM-1 and LFA-1 in the oral cavity which can lead to downstream bone resorption and increase in the rate of periodontitis." (PMID 28326084, 2017). "In addition, TLR2 and TLR4 mRNAs are significantly downregulated in the gingival tissue of patients with chronic periodontitis as compared to healthy persons, suggesting that the oral mucosa develops endotoxin tolerance in chronic periodontitis." (PMID 18799018, 2008). "Notably, our data are consistent with a study with Porphyromonas gingivalis, the etiologic agent of periodontitis, where MDSC induction was not affected by TLR2 deficiency in mice." (PMID 37524886, 2023). "For example, the TLR2 pathway has been confirmed both in the pathogenesis of periodontitis and peri-implantitis; LPS and TLR4 pathway has been widely studied for the regulation in periodontitis and peri-implantitis; and also other PRRs pathways should be considered." (PMID 36685503, 2022). "However, most of the studies on gene polymorphism of TLR-2 have considered that there is no obvious correlation between TLR-2 polymorphism and periodontitis." (PMID 32831974, 2020). "In total, ten publications have examined the role of TLR-2 rs5743708 genetic variation in periodontitis, suggesting that rs5743708 may not be related to the periodontal disease, which is consistent in previous papers." (PMID 32831974, 2020). "It is important to note the discrepancies between the reports: in the case of IFNG, IL6, IL8, TNF, and TLR2, the differences in promoter methylation between patients with periodontitis and healthy individuals observed in some studies have not been reproduced in independent analyses." (PMID 33256844, 2020). "Furthermore, the activation of TLR2 and TLR4 are found to be related with gingivitis and periodontitis in vivo, in line with our study where we found that the gingivitis biofilm induced more upregulation of TLR4 transcription compared to commensal and cariogenic biofilms." (PMID 31448244, 2019). "Interestingly, we observed that much like the primary human gingival epithelial cells, stimulation of epithelial cells in periodontitis saliva with TLR-2 or TLR-4 specific ligands induced cytokine secretion with differential kinetics and up-regulated TLR-2 and TLR-4 mRNAs." (PMID 30571680, 2018). "Thus, it appears that the upregulation of TLR2 is a marker of type 2 diabetes rather than a marker of periodontitis." (PMID 28536605, 2016). "In addition, TLR2, a pattern recognition receptor for LPS from Gram-negative bacteria such as P. gingivalis, is strongly expressed in the pocket epithelium of periodontal tissues with chronic periodontitis." (PMID 29234378, 2017).